ABCA1 (ATP binding cassette subfamily A member 1)
Diseases named in the same sentence as ABCA1 in open-access papers (continued):
Sharing a sentence is not in itself a finding about the gene and the disease.
familial Mediterranean fever (1 paper, 2013). Familial Mediterranean fever (FMF) is an autoinflammatory disorder characterized by recurrent short episodes of fever and serositis resulting in pain in the abdomen, chest, joints and muscles. "The same principle applies to other genes: ATP13A2 responsible for a juvenile onset of PD, GBA responsible for Gaucher’s disease, ABCA1 responsible for Tangier disease, and MEFV responsible for familial Mediterranean fever (FMF)." (PMID 23970884, 2013).
fatty acid metabolism disorder (1 paper, 2021). "In summary, the present study revealed the protective role of circRNA_0001805 against NAFLD-induced fatty acid metabolism disorder and inflammation through the direct regulation of the miR-106a-5p/miR-320a/ABCA1/CPT1 axis." (PMID 34789275, 2021).
Glucose intolerance (1 paper, 2021). Glucose intolerance (GI) can be defined as dysglycemia that comprises both prediabetes and diabetes. "A novel small molecule agonist of RXR, UAB126 could prevent high-fat diet induced glucose intolerance and retinoic acid isomer; 9ciRA balanced cholesterol homeostasis by regulating ABCA1 expression." (PMID 34578896, 2021). "A previous study showed that mice lacking of the pancreatic ABCA1 gene exhibited defective glucose-stimulated insulin secretion (GSIS) and glucose intolerance." (PMID 34578896, 2021).
HCMV infection (1 paper, 2018). "Sanchez and Dong demonstrated decreased protein expression of ABCA1 in the early stage of HCMV infection." (PMID 29409508, 2018).
Hyperbilirubinemia (1 paper, 2017). An increased amount of bilirubin in the blood. "ABCA1 protein levels were also significantly decreased in PBMCs from human participants with GS (hyperbilirubinemia) compared with normobilirubinemic control participants." (PMID 28455345, 2017).
Infertility (1 paper, 2022). "Although characteristics of ABCA1 KO mice mentioned here suggest that the mechanism explaining the infertility is complex, our recent evidence indicates that the absence of ABCA1 in KO eggs affects their cholesterol homeostasis." (PMID 36187480, 2022).
injury (1 paper, 2021). Damage inflicted on the body as the direct or indirect result of an external force, with or without disruption of structural continuity. "In animal models of brain injury, ApoE and ABCA1 expression were increased, presumably to facilitate this transport." (PMID 34830135, 2021).
insulinoma (1 paper, 2019). "The causal relationships between these proteins and the cholesterol efflux pathway mediated by ABCA1, which can help to sustain β-cell function, were evaluated in BRIN-BD11 insulinoma cells." (PMID 30819824, 2019).
irritable bowel syndrome (1 paper, 2018). Irritable bowel syndrome (IBS) is a chronic functional condition of the lower gastrointestinal (GI) tract characterized by abdominal pain or discomfort and disordered bowel habit (diarrhea, constipation, or fluctuation between the two). "For example, we see association among gene ABCA1 with HDL levels, total cholesterol levels, and irritable bowel syndrome (IBS)." (PMID 29545597, 2018).
kidney cancer (1 paper, 2026). Primary or metastatic malignant neoplasm involving the kidney. "Consistent with the results of kidney cancer cell lines, this resistance was canceled by CsA, and upregulation of ABCA1 expression was also observed in EpH4-Snail cells." (PMID 41521893, 2026).
leukopenia (1 paper, 2024). "The risk of recurrence of leukopenia in four or more cycles was increased by two independent genetic factors: ABCA1 rs4149339 common and rare homozygotes CC/TT (OR 2.66; 0.14–0.95; p = 0.04) and DPYD rs291583 homozygote GG (OR 2.80; 1.26–6.19; p = 0.011)." (PMID 39596349, 2024). "We found a higher risk of recurrent leukopenia in carriers of ABCA1 rs4149339 homozygotes CC and TT." (PMID 39596349, 2024).
lung fibrosis (1 paper, 2022). "The inhibition of MP release by endothelial cells using pantethine or by inactivating ATP-binding cassette transporter A1 (ABCA1), thereby inhibiting transport of PS to the outer leaflet, ameliorated skin and lung fibrosis in murine SSc." (PMID 35514984, 2022).
lymph node metastasis (1 paper, 2023). "Moreover, ABCA1 expression was elevated in high-grade GAC (P < 0.001) and was associated with the extent of tumor spread (T) and lymph node metastasis (N)." (PMID 37874419, 2023).
metastatic melanoma (1 paper, 2009). A melanoma that has spread from its primary site to another anatomic site. "In the majority of primary and metastatic melanomas ABCA1 is highly expressed." (PMID 20030852, 2009).
neuropathy (1 paper, 2023). A disorder affecting the nervous system that manifests with pain, tingling, numbness, and/or muscle weakness. "Although significant associations were found between SNPs in ABCA1 (rs2230806), ABCC2 (rs1885301, rs3740066, rs4148396) and CAMK2N1 (rs12023000) and CIPN in univariate analyses, none of these SNPs were associated with neuropathy in multivariate setting." (PMID 36672910, 2023).
pancreatic ductal adenocarcinoma (1 paper, 2015). An infiltrating adenocarcinoma that arises from the epithelial cells of the pancreas. "The expression of ABC transporters (including ABCA1) have been associated with deregulation in one of the most drug-resistant cancers, the pancreatic ductal adenocarcinoma (PDAC)." (PMID 25749516, 2015).
paroxysmal AF (1 paper, 2021). "Similarly, in patients with persistent AF, Non-ABCA1 CEC was significantly impaired compared to that in patients with paroxysmal AF." (PMID 33574408, 2021). "Consequently, Non-ABCA1 CEC was significantly compromised in patients with persistent AF compared with those with paroxysmal AF." (PMID 33574408, 2021).
peripheral artery disease (1 paper, 2021). "CAD with concomitant carotid artery disease or peripheral artery disease is accompanied by decreased ABCA1 gene expression in EAT." (PMID 34837967, 2021). "ABCA1 mRNA levels in EAT samples were reduced in the subgroup of patients with CAD and concomitant carotid artery disease or peripheral artery disease compared with the NCAD group (p = 0.024)." (PMID 34837967, 2021). "In addition, ABCA1 mRNA levels in EAT were reduced in the subgroup of patients with CAD and concomitant carotid artery disease or peripheral artery disease (i.e. proven multifocal atherosclerosis) compared with the NCAD group." (PMID 34837967, 2021). "However we identified a subgroup of CAD patients with reduced ABCA1 mRNA levels in EAT who underwent additional examination and had a proven concomitant carotid artery disease or a peripheral artery disease." (PMID 34837967, 2021). "We did not analyze ABCA1 and ABCG1 DNA methylation levels in the subgroup of patients with CAD and concomitant carotid artery disease or peripheral artery disease separately, as only three samples from this subgroup were available for DNA methylation analysis." (PMID 34837967, 2021).
peripheral nerve injury (1 paper, 2023). Injury to a peripheral nerve. "Interestingly, Abca1 was closely associated with Th1 cell infiltration in the model of peripheral nerve injury." (PMID 37264427, 2023).
polycystic ovary syndrome (1 paper, 2011). A disorder that manifests as multiple cysts on the ovaries. "This study aims at exploring the association between metabolic, oxidative stress parameters (including malondialdehyde, (MDA) nitric oxide (NO) and disulfide levels (SH)) and demographic parameters and ABCA1 gene polymorphisms in polycystic ovary syndrome patients." (PMID 22035022, 2011).
prediabetes (1 paper, 2024). "Expression of the 3 LXR target genes, ABCG1, ABCA1, and MYLIP, was inversely associated with risk of prediabetes/T2D, with ABCG1 associations (HR, 1.33 per 1-SD decrease; 95% CI, 1.14–1.56; P = 3.63 × 10–4 in the full model) being similar to that of MYLIP." (PMID 38747290, 2024). "Our data showed that, in addition to coexpressed ABCG1, ABCA1, and MYLIP, expression of NR1H2 (encoding LXRβ) itself was also inversely associated with incident prediabetes/T2D, suggesting, for the first time to our knowledge, that dysregulated LAAMP is a major risk factor for T2D." (PMID 38747290, 2024). "During a median 6-year follow-up, lower expression of 3 highly correlated LXR target genes — ABCG1 and ABCA1 (cholesterol efflux) and MYLIP (cholesterol uptake suppression) — and not other CMTN genes, was significantly associated with higher risk of incident prediabetes/T2D." (PMID 38747290, 2024).
primary biliary cholangitis (1 paper, 2021). Primary biliary cholangitis (PBC) is a chronic and slowly progressive cholestatic liver disease of autoimmune etiology characterized by injury of the intrahepatic bile ducts that may eventually lead to liver failure. "Furthermore, in primary biliary cholangitis (PBC) patients, mRNA for LXRβ correlated with the increased levels of ABCA1 mRNA found in liver biopsy samples." (PMID 33252713, 2021).
primary hypertension (1 paper, 2024). "The expression of miR-33a is conversely related to ABCA1/G1 in monocytes of patients with primary hypertension." (PMID 38968577, 2024).
prostate (1 paper, 2022). "Of the metabolic targets of LXR agonists in cancer, ABCA1 is the best characterized, the reduced expression of which is associated with prostate carcinogenesis and its upregulation is induced by LXR agonists." (PMID 38089448, 2022).
prostate intraepithelial neoplasia (1 paper, 2024). A neoplastic proliferation of the epithelial cells that line the acini and the ducts of the prostate gland. "In a high-grade prostate intraepithelial neoplasia mouse model, the overexpression of fatty acid synthase and ABCA1 knockout led to prostate intraepithelial neoplasia progressing to invasive PCa with a 100% penetrance rate." (PMID 39200296, 2024).
renal carcinoma (1 paper, 2026). A carcinoma arising from the epithelium of the renal parenchyma or the renal pelvis. "(A) Enhancement of growth inhibitory effect of NC on human renal carcinoma cells by co-treatment with an ABCA1 inhibitor cyclosporin A (CsA)." (PMID 41521893, 2026). "Therefore, we examined the effect of ABCA1 inhibitor CsA and ACAT inhibitor TMP-153 on the EpH4-Snail model and renal carcinoma cells." (PMID 41521893, 2026).
Renal cyst (1 paper, 2020). A fluid filled sac in the kidney. "We tested renal cysts within kidney tissue obtained from the named mouse model for ICA- and HIF-1α-dependent effects on MIF as well as ABCA1 expression by immunohistochemistry." (PMID 32885302, 2020).
retinal (1 paper, 2021). "While ABCA1 has been implicated in retinal inflammation and retinal ganglion cell apoptosis, recent research has also demonstrated that ABCA1 has a role in regulating IOP through aqueous humor dynamics." (PMID 34440309, 2021).
schizophrenia (1 paper, 2009). A major psychotic disorder characterized by abnormalities in the perception or expression of reality. "To test whether other CED orthologs in human are involved in schizophrenia, we conducted association analyses of the GULP1, ABCA1 and ABCA7 genes that are the human orthologs of the CED-6 and CED-7 genes." (PMID 19721717, 2009). "We typed 11 and 5 SNPs for the ABCA1 and ABCA7 genes to test whether these genes in the phagocytosis pathway may impact on risk for schizophrenia." (PMID 19721717, 2009).
scrapie (1 paper, 2010). A fatal disease of the nervous system in sheep and goats, characterized by pruritus, debility, and locomotor incoordination. "When extending the comparisons between differentially expressed genes to include two mouse scrapie models only 1 gene (GFAP) is in common for all 4 studies and two when comparing the 3 mammalian (GFAP, ABCA1)." (PMID 21042590, 2010).
Smith-Lemli-Opitz syndrome (1 paper, 2018). Smith-Lemli-Opitz syndrome (SLOS) is characterized by multiple congenital anomalies, intellectual deficit, and behavioral problems. "A recent study in humans revealed also a highly significant correlation between maternal ABCA1 genotypes and the severity in Smith-Lemli-Opitz syndrome (SLOS)." (PMID 30096856, 2018).
stenosis (1 paper, 2021). "Therefore, the objectives of this study were to evaluate the expression of ATP binding cassette transporter 1 (ABCA1) and validate its target microRNA (miRNA) candidates in human carotid stenosis arteries to identify its potential as a biomarker." (PMID 34440128, 2021).
systemic sclerosis (1 paper, 2017). A chronic disorder, possibly autoimmune, marked by excessive production of collagen which results in hardening and thickening of body tissues. "As it inhibits MV release, it so prevents systemic sclerosis in mice, as does knocking out the ABCA1 gene." (PMID 28486412, 2017).
Thrombocytopenia (1 paper, 2012). A reduction in the number of circulating thrombocytes. "It is known that ABCA1 is involved in inflammation, and various alterations have been reported in ABCA1-deficient platelets and Tangier patients including mild thrombocytopenia and bleeding tendencies." (PMID 23152888, 2012).
thyroid (1 paper, 2023). "To clarify the role of ABCA1 in lung metastasis of PTC, we investigated its expression in several immortalized thyroid and cancer cells." (PMID 36672209, 2023).
xanthoma (1 paper, 2022). A non-neoplastic disorder characterized by a localized collection of histiocytes containing lipid. "On the contrary, ABCA1-mediated HDL-CEC in patients with ATX raised as compared to no ATX FH patients and did not correlate with CLC, suggesting its minor role in CLC level and xanthoma formation." (PMID 35897824, 2022).
β cell deficiency (1 paper, 2022). "β cell deficiency for the ATP binding cassette transporter A1 (ABCA1), which mediates the efflux of cellular cholesterol, leads to altered intracellular cholesterol homeostasis and impaired insulin secretion in mice." (PMID 36232796, 2022).
tumor (146 papers, 2012 to 2026). "For instance, adding LXR agonists to these systems can improve the removal of cholesterol from tumor-associated macrophages (TAMs), activate ABCA1, and transform them from an immunosuppressive to an immune-supporting state." (PMID 41304832, 2025). "Patients with UCEC tumours with “mutation” as the main type had the highest frequency of ABCA1 gene changes (> 10%)." (PMID 40297807, 2025). "Cluster 1 contained genes significantly upregulated in AMPKα1/α2–deficient tumor-infiltrating Treg cells and included genes encoding chemokines (Ccl2, Ccl7, Ccl8), modulators of lipid metabolism (Cd36, Pparg, Lpl, Abca1), and glycolytic enzymes (Hk2, Hk3)." (PMID 40100289, 2025). "ABCA1 is strongly expressed in both malignant cholangiocytes (log2FC: 23.16; padj = 1.35 × 10−117) and tumor-associated macrophages (log2FC: 4.09; padj = 2.45 × 10−279), suggesting dysregulated cholesterol efflux in both epithelial and immune compartments." (PMID 41373405, 2025). "It was found that simvastatin repolarized tumor-associated macrophages (TAMs) by regulating the cholesterol-related LXR/ABCA1 pathway, promoting the phenotypic shift of TAMs from the M2 type to the M1 type." (PMID 41467185, 2025). "According to one study, promoter hypermethylation in prostate cancer causes ABCA1 downregulation, which raises intracellular cholesterol levels and creates an environment that is favorable for tumor growth." (PMID 38540127, 2024). "Combined with the clinical phenotypes in TCGA-STAD cohort, we found that Scissor + cells associated with the “Dead,” “Tumor,” “Grade 3,” and “N1–3” phenotypes exhibited a higher distribution of ABCA1(+) macrophages." (PMID 37874419, 2023). "Missense mutations in ABCA1 contribute to tumor progression in patients with chronic myelomonocytic leukemia." (PMID 37545500, 2023). "For example, depletion of ABCA1 and loss of cholesterol efflux in prostate cancer led to increased tumor growth." (PMID 37312227, 2023). "Intriguingly, among these 11 significantly associated genes, Lrp1, Abca1, Map4k4, Vegfa, and Nf1 regulate cell efferocytosis, micropinocytosis, and endocytic activities in DCs, macrophages, and tumor cells." (PMID 37508356, 2023). "In cancer cells, ABCA1 has been associated multidrug resistance as a drug efflux transporter and it is a key component of the tumour microenvironment remodelling." (PMID 36439419, 2022). "Loss of ABCA1 expression results in high intracellular cholesterol levels, which creates an environment conducive to tumor progression." (PMID 34281263, 2021). "It was shown that myeloid specific deficiency of Abcg1 or Abca1 was associated with decreased tumor growth, increased polarization of TAMs towards M1 phenotype, and decreased numbers of specific MDSCs subsets in the tumors." (PMID 31374929, 2019). "According to the data presented here, before diagnosis, ABCA1 can be considered a high‐risk factor that promotes tumour growth and dissemination of the primary lesion." (PMID 30098223, 2018). "In mice with myeloid-specific loss of ABCA1 (Abca1−M/−M; A1−M/−M), tumor growth was inhibited by ∼4.8-fold relative to wild type (WT) animals." (PMID 29069761, 2017). "Furthermore, we found that several upregulated genes in those enhanced subclones, including SYT14, CREB5, and ABCA1, were associated with drug resistance and tumor proliferation in previous reports." (PMID 37324492, 2023). "It is believed that mutations or a low expression of ABCA1 promote tumor development because of cholesterol accumulation, but the disruption of the asymmetric cholesterol distribution may be also a cause." (PMID 36395885, 2022). "In the mechanical microenvironment, simvastatin repolarizes tumor-associated macrophages (TAM) and promotes M2-to-M1 phenotype switching of macrophages via cholesterol-associated LXR/ABCA1 regulation, thereby remodeling the tumor microenvironment and inhibiting EMT." (PMID 34303383, 2021).